ZNF480 (zinc finger protein 480)
Description:
Involved in transcriptional regulation as an activator.
Synonyms: MGC32104
Tractability: PROTAC: UniProt records ubiquitination sites on it; ubiquitination databases record sites on it.
Gene: Protein-coding gene on chromosome 19 (52,297,167 to 52,325,926, forward strand). Ensembl gene ENSG00000198464.
Subcellular location: Nucleus
Subcellular location (Human Protein Atlas): Nucleoplasm; Cytosol
Pathways (Reactome):
Gene expression (Transcription): Generic Transcription Pathway
Gene Ontology:
Molecular function: protein binding; DNA-binding transcription factor activity, RNA polymerase II-specific; RNA polymerase II cis-regulatory region sequence-specific DNA binding
Biological process: regulation of transcription by RNA polymerase II; regulation of DNA-templated transcription
Cellular component: nucleoplasm; nucleus
Genetic constraint (gnomAD): Loss-of-function variants: 15 observed, 12.94 expected, observed/expected ratio (o/e) 1.16, 90% interval 0.77 to 1.74. The upper end of that interval is the gene's LOEUF score, 1.74, which puts it in group 6 of 6, group 1 being the genes least tolerant of losing a copy. Missense variants: 589 observed, 646.16 expected, observed/expected ratio (o/e) 0.91, 90% interval 0.85 to 0.98. Synonymous variants: 216 observed, 224.99 expected, observed/expected ratio (o/e) 0.96, 90% interval 0.86 to 1.08.
Homologues: Orthologues: chimpanzee ZNF480 (99% identical), mouse Zfy1 (22% identical), rat Zfy1 (22% identical), mouse Zfy2 (21% identical), tropical clawed frog zfx (21% identical), zebrafish zfx (20% identical). Paralogues in human: ZNF610 (61% identical), ZNF583 (46% identical), ZNF570 (45% identical), ZNF256 (40% identical), ZNF304 (40% identical), ZNF551 (40% identical), ZNF549 (40% identical), ZSCAN20 (39% identical), ZNF548 (39% identical), ZSCAN2 (39% identical), ZNF587B (39% identical), ZNF792 (39% identical), and 26 more.
Diseases named in the same sentence as ZNF480 in open-access papers:
ZNF480 is named in the same sentence as 2 diseases in open-access papers, as found by Europe PMC text mining. Sharing a sentence is not in itself a finding about the gene and the disease. The quoted sentences say what the papers report.
schizophrenia (2 papers, 2013 to 2018). A major psychotic disorder characterized by abnormalities in the perception or expression of reality. "A previous study found two de novo nonsense variants of ZNF480 in schizophrenia patients, and variants in other C2H2-type zinc finger proteins have been reported to be associated with ID." (PMID 30477169, 2018).
tumor (1 paper, 2018). "It not only reflects liver damage but also regulates other biological processes such as triglyceride and cholesterol metabolism by silencing target genes and the upregulation of ZNF480 resulting in tumor cell death." (PMID 30344796, 2018).